WWP2 (WW domain containing E3 ubiquitin protein ligase 2)
Diseases named in the same sentence as WWP2 in open-access papers (continued):
Sharing a sentence is not in itself a finding about the gene and the disease.
thyroid cancer (2 papers, 2018 to 2025). "In contrast, significantly reduced WWP2 expression was observed in eight tumor types: BRCA, COAD, KICH, KIRC, LUAD, LUSC, THCA (thyroid carcinoma), and UCEC." (PMID 41387673, 2025). "A study in thyroid cancer cells showed that depletion of hypoxia-inducible factor-1α (HIF-1α) resulted in a decrease in WWP2 expression, suggesting a possible mechanism by which hypoxic conditions in the tumor may result in increased WWP2 expression." (PMID 29954076, 2018).
Type 2 diabetes (2 papers, 2023 to 2025). "However, a separate study reported that E3 ligase WWP2 increases DDX3X K63-polyubiquitination, promoting its proteasomal degradation in Type 2 diabetes." (PMID 41198618, 2025).
Arrhythmia (1 paper, 2025). Any cardiac rhythm other than the normal sinus rhythm. "In a murine model of arrhythmia, PPP1R3A is significantly overexpressed during the initial stages, a period when WWP2 is only marginally upregulated." (PMID 41362701, 2025). "The E3 ubiquitin ligase WWP2 and the protein phosphatase 1 regulatory subunit PPP1R3A exhibit a dynamic and inverse regulatory relationship during the progression of arrhythmia‐induced cardiac damage." (PMID 41362701, 2025).
co-infection (1 paper, 2024). "In the present case, co-infection by both VZV and HSV-1, together with WWP2 p.R841H carriage, may have been required for the development of HSE." (PMID 38730242, 2024).
colon cancer (1 paper, 2024). "We then used the Ualcan dataset to select four candidate E3 ligases (TRIM25, HECTD3, NEDD4L, WWP2) whose mRNA levels were lower in colon cancer tissue samples compared to normal colon tissues." (PMID 38803048, 2024).
COVID-19 (1 paper, 2021). A disease caused by infection with severe acute respiratory syndrome coronavirus 2. "We found that WWP1, WWP2, SMURF1, and NEDD4 mRNA are overexpressed in COVID-19 vs. SARS-CoV-2 negative patients in nasopharyngeal and oropharyngeal swab cells, as well as in the lung of affected patients and in mouse models of COVID-19." (PMID 33762578, 2021). "NEDD4 (FC = + 2.06, p ≤ 0.005), WWP1 (FC = + 1.85, p ≤ 0.0005), WWP2 (FC = + 4.11; p < 0.005) and SMURF1 (FC = + 1.7, p ≤ 0.05) showed a significant overexpression in nasopharyngeal and oropharyngeal swabs of COVID-19 positive patients compared to negative patients." (PMID 33762578, 2021).
herpes simplex encephalitis (1 paper, 2024). Herpes simplex virus encephalitis (HSE) is caused by the infection of the central nervous system by Herpes simplex virus (HSV) that could have a devastating clinical course and a potentially fatal outcome particularly with delay or lack of treatment. "Following genome-wide genetic analyses, we identified a previously uncharacterized and very rare heterozygous variant in the E3 ubiquitin ligase WWP2, in a 14-month-old girl with herpes simplex encephalitis." (PMID 38730242, 2024).
IgA nephropathy (1 paper, 2024). "A significant correlation between the WWP2-positive area and fibrosis in the tubulointerstitial region was detected in a multicenter cohort of patients with CKD (r=0.274, P = 0.001) and confirmed in two cohorts of patients with IgA nephropathy." (PMID 38502123, 2024).
Nephropathy (1 paper, 2024). A nonspecific term referring to disease or damage of the kidneys. "Patients with moderate CKD (stage 3–4) showed higher expression of interstitial WWP2 when compared with those having mild CKD (stage 1–2), regardless of the original insult leading to the kidney damage." (PMID 38502123, 2024).
neuroblastoma (1 paper, 2022). Neuroblastoma (NB) is the most common solid, extracranial childhood tumor. "For additional cellular experiments, we used CRISPR-Cas9 to genetically delete WWP2 in neuroblastoma SH-SY5Y cells." (PMID 35331737, 2022). "Finally, we observed that WWP2 KO SH-SH5Y neuroblastoma cells using CRISPR-Cas9 showed a defect in mitophagy, which could be rescued by WWP2Y369E transfection." (PMID 35331737, 2022).
non-small cell lung carcinoma (1 paper, 2025). A group of at least three distinct histological types of lung cancer, including non-small cell squamous cell carcinoma, adenocarcinoma, and large cell carcinoma. "Another dual aneuploidy-targeting compound, etomidate, reduces the expression of the oncogenic protein WWP2, thereby limiting cell proliferation and inducing apoptosis in non-small cell lung cancer." (PMID 40565600, 2025).
Obesity (1 paper, 2025). Accumulation of substantial excess body fat. "WWP2 is an E3 ubiquitin ligase; experimental data show that reduced WWP2 aggravates diabetic endothelial injury by promoting DDX3X ubiquitination and degradation, linking obesity-related metabolic stress to endothelial barrier dysfunction." (PMID 41340073, 2025).
oral squamous cell carcinomas (1 paper, 2014). "However, little is known about the mechanisms and roles of WWP2 in human malignancies including oral squamous cell carcinomas (OSCCs)." (PMID 25621296, 2014).
Parkinson disease (1 paper, 2024). A progressive degenerative disorder of the central nervous system characterized by loss of dopamine producing neurons in the substantia nigra and the presence of Lewy bodies in the substantia nigra and locus coeruleus. "Benserazide, a well-tolerated prodrug used in combination with Levodopa to treat Parkinson’s disease, was identified in a screen for small molecules capable of binding to the Nedd4 family members WWP1 and WWP2 and interfering with the binding of PY-containing peptides." (PMID 39459900, 2024).
plantar fibromatosis (1 paper, 2023). A superficial fibromatosis arising from soft tissue of the plantar regions. "For example, in humans, a SNP (rs62051384) located within WWP2 is associated with plantar fibromatosis, a rare fibrous hyperproliferation of the deep connective tissue of the foot." (PMID 36658473, 2023).
renal cell carcinoma (1 paper, 2023). "It was reported that LAPTM5 recruited WWP2 to mediate lysosomal degradation to drive lung metastases of renal cell carcinoma." (PMID 38102722, 2023).
renal fibrosis (1 paper, 2024). A final common manifestation of a wide variety of chronic kidney diseases characterized by glomerulosclerosis and tubulointerstitial fibrosis. "WWP2 deficiency promoted myofibroblast proliferation and halted profibrotic activation, reducing the severity of renal fibrosis in vivo." (PMID 38502123, 2024). "WWP2 regulates the metabolic reprogramming of profibrotic myofibroblasts by a WWP2-PGC-1α axis, and WWP2 deficiency protects against renal fibrosis in CKD." (PMID 38502123, 2024). "After 14 days of UUO, there was significantly mitigated renal fibrosis in WWP2−/− mice, which showed approximately 50% reduction in cortical fibrosis and decreased collagen deposition compared with UUO WT mice." (PMID 38502123, 2024). "A combination of lineage-tracing studies and cell type–specific WWP2 targeting can conclusively establish the broad significance of WWP2-mediated myofibroblast metabolism in renal fibrosis." (PMID 38502123, 2024). "Here, we investigate WWP2 in renal fibrosis and in the metabolic reprograming of myofibroblasts in CKD." (PMID 38502123, 2024). "To test this hypothesis, we investigated human CKD kidneys, developed cellular and mouse models, and integrated single-cell transcriptomics with metabolic analyses to characterize the function of WWP2 in renal fibrosis." (PMID 38502123, 2024). "Despite the importance of tubular cells in renal fibrosis, our data suggest that the contribution of WWP2 in regulating these cells in fibrosis is limited, and this does not seem to occur through tubular proinflammatory activity or the secretion of profibrotic factors." (PMID 38502123, 2024). "Our work adds a previously unknown metabolic function of WWP2 in renal myofibroblasts and proposes WWP2 as a new druggable target to ameliorate renal fibrosis." (PMID 38502123, 2024). "However, the effect of WWP2 deficiency on interstitial fibrosis was not apparent at 7 days of UUO, a time point that coincides with mild–moderate renal fibrosis." (PMID 38502123, 2024).
Salmonella Infections (1 paper, 2020). Infections with bacteria of the genus SALMONELLA. "A recent study shows that the NEDD4 family HECT E3 ubiquitin ligase WWP2 is required for SteD-dependent ubiquitination of mature MHCII during salmonella infection." (PMID 33329564, 2020). "WWP2 has also been shown to ubiquitinate and deplete the surface expression of mature MHCII, thereby suppressing DC-mediated T cell activation during Salmonella infection." (PMID 33329564, 2020).
squamous cell carcinoma (1 paper, 2018). A carcinoma arising from squamous epithelial cells. "In squamous cell carcinoma, WWP2-mediated loss of PTEN accelerated tumor cell growth and activation of the PI3K/AKT signaling pathway." (PMID 29954076, 2018). "WWP2 appears to regulate the expression of the well characterized tumor suppressor phosphatase and tensin homolog (PTEN) in endometrial cancer and squamous cell carcinoma." (PMID 29954076, 2018).
ZIKV infection (1 paper, 2024). "NSC2805, a natural chemical inhibitor of WWP2, was employed to investigate the role of WWP2 in ZIKV infection in host cells." (PMID 39159062, 2024). "This reinforces the idea that WWP2 inhibits ZIKV infection by regulating the NS1 protein, thereby preventing ZIKV infection." (PMID 39159062, 2024). "To elucidate the impact of WWP2 on ZIKV infection, we employed overexpression of WWP2 in diverse cell types and evaluated ZIKV infectivity by measuring both the viral RNA level within cells and viral particle abundance in cell supernatants." (PMID 39159062, 2024). "Across these diverse models, the expression level of the WWP2 gene consistently exhibited an up‐regulation following ZIKV infection." (PMID 39159062, 2024). "We assessed the impact of ZIKV infection on WWP2 levels in SH‐sy5y and 293T cells using qRT‐PCR and Western Blot." (PMID 39159062, 2024). "These in vivo experiments further underscore the pivotal role of WWP2 in inhibiting ZIKV infection." (PMID 39159062, 2024). "These collective findings imply a significant role for host WWP2 in the process of ZIKV infection." (PMID 39159062, 2024). "The results showed that WWP2 lost its inhibitory effect on ZIKV infection after MG132 treatment." (PMID 39159062, 2024). "The results unveiled an up‐regulation of WWP2 expression during ZIKV infection." (PMID 39159062, 2024). "The mammalian E3 ligase WWP2 mediates the ubiquitination and degradation of NS1, thereby restricts ZIKV infection in mammalian hosts." (PMID 39159062, 2024). "WWP2‐mediated NS1 ubiquitination leads to NS1 degradation via the ubiquitin‐proteasome pathway, thereby inhibiting ZIKV infection in mammalian hosts." (PMID 39159062, 2024).
cancer (28 papers, 2014 to 2025). A tumor composed of atypical neoplastic, often pleomorphic cells that invade other tissues. "WWP2 has been implicated in several cancers, influencing tumor progression by modulating key cell cycle proteins and apoptotic pathways." (PMID 39949609, 2024). "Indeed, dysregulation of WWP2 has been associated with several types of cancer and WWP2 interacts with another tumour suppressor—phosphatase and tensin homolog (PTEN)." (PMID 32526160, 2020). "Considering these findings, further research is urgently needed to elucidate the roles of ARIH1, SIAH2, UBR5, and WWP2 in modulating mitophagy, mitochondrial homeostasis, and drug resistance in cancer." (PMID 40004017, 2025). "The HECT E3 ubiquitin ligases 1 (WWP1) and 2 (WWP2) are responsible for the ubiquitin-mediated degradation of key tumour suppressor proteins and are dysregulated in various cancers and diseases." (PMID 39223706, 2024). "While WWP1 has been extensively studied for its role in cancer via ubiquitin-mediated degradation, WWP2 shares structural and functional similarities with WWP1 but performs distinct roles, particularly in regulating the cell cycle and protein degradation." (PMID 39949609, 2024). "In summary, the mutation status and RNA expression levels of WWP family members, particularly WWP1 and WWP2, are emerging as important prognostic factors in various cancers." (PMID 39949609, 2024). "WWP2 has been shown to promote the PI3K/AKT pathway by the degradation of PTEN in different cancers." (PMID 37568787, 2023). "WWP2 binds to substrates in many signaling pathways, including the PI3K/Akt and TGF-β pathways, and is linked to cancer and immune system modification." (PMID 36293239, 2022). "These signalling pathways are often disrupted in human malignancies, and several NEDD4 family members, including NEDD4, NEDD4L, SMURF1, SMURF2, WWP1 and WWP2, also have altered expression or splicing in cancer." (PMID 31546607, 2019). "As a result, Cdh1 modulates the PI3K/Akt signaling pathway by influencing WWP2-mediated degradation of PTEN in cancer cells to govern tumorigenesis." (PMID 27462441, 2016). "We next sought to investigate how the Cdh1/WWP2 signaling axis impinges on the tumorigenicity of cancer cells." (PMID 27462441, 2016). "As a result of reducing cellular growth of the shWWP2 transfected cells, we investigated PTEN expression, reported to be associated with WWP2, following the PI3K-AKT pathway, which is activated frequently in many cancers." (PMID 25621296, 2014). "The negative regulation of WWP2 on Notch signaling activity is more prominent in Notch3-overexpressing cancer cells." (PMID 25356737, 2014). "For example, reagents upregulating the expression of WWP2 and gene therapy approach by re-introducing WWP2 into cancer cells are worth pursuing for the treatment of cancers that have developed dependence on Notch3 signaling." (PMID 25356737, 2014). "One mechanistic hypothesis resulting from this study is that etomidate represses WWP2 and TGFβ signaling in cancer cells reliant on these proliferative pathways." (PMID 40565600, 2025). "WWP2 is a well‐known E3 ubiquitination ligase and several studies have demonstrated aberrant expression of E3 ubiquitination ligases in a variety of diseases, especially cancers." (PMID 39166861, 2024). "Given that the coimmunoprecipitation data showed that WWP2 was an interacting partner of LATS1, we speculated that the cancer-promoting functions of WWP2 might be related to the Hippo-YAP1 pathway." (PMID 36803368, 2023). "Therefore, the lack of Cdh1 activates WWP2, which in turn causes a decrease in the abundance of WWP2 substrates such as PTEN, which stimulates PI3K/Akt oncogenic signaling and promotes cancer growth." (PMID 36293239, 2022). "Therefore, WWP2 inhibitors should be cautiously used according to the individualized treatment strategy of patients with cancer." (PMID 34943817, 2021).
cancer (continued). "WWP2 is an E3 ligase associated with carcinogenesis and spread, which can cause the ubiquitin-dependent degradation of specific tumor suppressor proteins (such as Oct4 and PTEN) in many cancers." (PMID 34943817, 2021). "In addition to having physiological roles such as embryogenesis and T-cell activation, WWP2′s oncogene role in cancer cells is being revealed by accumulating data." (PMID 32756305, 2020). "In GC cells, WWP2 enhances the growth and viability of cancer cells via the downregulation of PTEN." (PMID 32756305, 2020). "As elevation of Cdk activity has been found in most cancer cells, Cdh1 might largely exist in an APC-free population in these cancer cells, which directly interacts with WWP2 to facilitate its auto-inhibition." (PMID 27462441, 2016). "Furthermore, ectopic expression of WWP2 decreased tumor development in a mouse xenograft model and suppressed the Notch3-induced phenotypes including increase in cancer stem cell-like cell population and platinum resistance." (PMID 25356737, 2014). "This discovery may provide a novel strategy that WWP2 may be a useful biomarker of proliferation and a possible therapeutic target for developing anti-cancer drugs for human OSCCs." (PMID 25621296, 2014). "We have shown that WWP2 directly interacts with and mono-ubiquitinates post-secretase cleaved Notch3 fragments, promoting their sorting to and degradation in lysosomes, thereby suppressing Notch3 signaling activity in cancer cells." (PMID 25356737, 2014). "This article is the first study, to our knowledge, that delineates the Notch3 interacting network, and demonstrates that one of the Notch3 interacting proteins, WWP2, an E3 ubiquitin-protein ligase, plays a major role in negative regulation of Notch3 signaling in cancer cells." (PMID 25356737, 2014). "Wild-type WWP2 but not ligase-deficient mutant WWP2 increases mono-ubiquitination of the membrane-tethered Notch3 fragment, therefore attenuating Notch3 pathway activity in cancer cells and leading to cell cycle arrest." (PMID 25356737, 2014). "Other E3 ligases, mainly the HECT domain E3 ligases such as WWP1, WWP2, NEDD427–29 also adopt similar closed autoinhibited state, in which its multiple WW domains sequester HECT using a multi-lock mechanism and phosphorylation of linker or cancer associated mutation relieve autoinhibition." (PMID 38104184, 2023). "Besides, some NEDD4 E3 ligase family genes might affect the prognosis regarding different cancer types to different extents such as WWP2 and Smurf2." (PMID 37291499, 2023). "Therefore, the use of chemical inhibitors for WWP2 will be advantageous in cancer prevention." (PMID 37568787, 2023). "Therefore, inducing Cdh1 abundance may present a potential therapeutic approach for the treatment of human cancers with high E3 ligase activity of WWP2." (PMID 27462441, 2016). "This study expands the non-anaphase-promoting complex/cyclosome function of Cdh1 in regulating the NEDD4 family E3 ligases, and further suggested that enhancing Cdh1 to inhibit the E3 ligase activity of WWP2 could be a promising strategy for treating human cancers." (PMID 27462441, 2016). "WWP2-expressing tumors developed at a slower rate, and pulmonary metastatic nodules were fewer in numbers in mice injected orthotopically with MDA-MB-231 cancer cells in mammary fat pads." (PMID 37568787, 2023). "WWP2 influences PTEN’s degradation through a ubiquitylation-dependent pathway, regulating cellular apoptosis and increasing the development of cancer in a nude mice (DU145) xenograft, and the knockdown of WWP2 was shown to decrease tumor growth." (PMID 36293239, 2022). "WWP2, another member of the NEDD4 family, possessing similar functional domains with WWP1, was reported to be markedly correlated with tumorigenesis and progression in several cancers." (PMID 36803368, 2023).
cancer (continued). "A systematic search in different electronic databases indicated that, among HECT-type E3 ligases, members of the NEDD4 family including NEDD4-1, NEDD4L, SMURF-1, SMURF-2, WWP1, WWP2, and ITCH have been investigated in many various cancers with defective autophagy, as reviewed in next sections." (PMID 36918822, 2023). "Based on our findings and others’, we speculate that WWP2-mediated LATS1 ubiquitination and subsequent YAP1 activation may promote tumor progression, thereby providing novel targets for clinical cancer therapy." (PMID 36803368, 2023). "In conclusion, these data demonstrated that the activation of LAPTM5 in lung metastases is a common molecular event shared by several types of human cancer, and that the LAPTM5/WWP2-based lysosomal regulatory pathway mediates the ubiquitination and degradation of BMPR1A." (PMID 35842443, 2022). "It would be interesting to further analyze if a negative correlation exists between WWP2 and p73 expression in human cancers, which would further strengthen their functional link in tumorigenesis." (PMID 25071155, 2014). "Importantly, depletion of endogenous Cdh1 in these cancer cell lines significantly suppressed the protein levels of WWP2 but not other NEDD4 family proteins examined." (PMID 27462441, 2016).